NME2 (NME/NM23 nucleoside diphosphate kinase 2)
Diseases named in the same sentence as NME2 in open-access papers (continued):
Sharing a sentence is not in itself a finding about the gene and the disease.
infection (2 papers, 2021 to 2024). The state of being infected such as from the introduction of a foreign agent such as serum, vaccine, antigenic substance or organism. "Genes involved in pyrimidine metabolism (RRM2, CTPS1, TK1, NME1, NME2, and UCK2) were induced after infection with swH1N1 compared to huH1N1." (PMID 39247193, 2024). "Furthermore, other genes related to the pyrimidine pathway, namely NME1, NME2, and UCK2, were significantly higher expressed after infection with the swH1N1 relative to the pigs infected with huH1N1, albeit occasionally with modest fold changes." (PMID 39247193, 2024). "However, what was striking was the lower abundancy of proteins involved in response to infection (ISG15, NME2, IFNγ, and C3)." (PMID 34962717, 2021).
NME2 also shares sentences with these, for which no sentence is quoted: Hyperglycemia (4 papers); Arrhythmia (3); acute myeloid leukaemia (2); cardiovascular diseases (2); cervical carcinoma (2); diabetes (2); diabetic retinopathy (2); retinopathy (2); squamous cell carcinoma (2); Alzheimer disease (1); atherosclerosis (1); cardiac hypertrophy (1); central precocious puberty (1); cholangiocarcinoma (1); diabetic cardiomyopathy (1); endometrial carcinoma (1); esophageal tumors (1); heart failure (1); hepatocellular carcinoma (1); Impaired glucose tolerance (1); leishmaniasis (1); liver cancer (1); metastatic cancer (1); myopathy (1); non-small cell lung carcinoma (1); oral squamous cell carcinoma (1); pancreatic carcinoma (1); prediabetes (1); Rett syndrome (1); sarcopenia (1).
A further 3 diseases each share a sentence with NME2 in 1 paper.